IL6 (interleukin 6)
Diseases named in the same sentence as IL6 in open-access papers (continued):
Sharing a sentence is not in itself a finding about the gene and the disease.
breast cancer (continued). "Then, through Spearman's rank correlation, we showed that high expression of NF-κB modulates positively the IL-6 and TNF-α expression levels in mammary tumors." (PMID 26989335, 2016). "Inflammatory cytokines including interleukins (IL-1β, IL-2, IL-6, IL-8, IL-12), tumor necrosis factor alpha (TNF-α), and interferon gamma (IFN-γ) are key inflammatory mediators of interest in breast cancer progression." (PMID 26970739, 2016). "In our previous report, expression of TG2 and expression of IL-6 were found to correlate with one another, and TG2 was found to promote aggressive phenotypes in breast cancer cells through IL-6." (PMID 27609180, 2016). "Very recently, IL-6 has been suggested as a major factor influencing resistance to trastuzumab, a therapeutic HER2 antibody, in breast cancer." (PMID 26840088, 2016). "G-CSF, M-CSF, IL-6, MIF and TGF-β1 were verified to promote the differentiation of myeloid cells into MDSCs in 4T1 mammary tumor BALB/c mice." (PMID 27542274, 2016). "IL-6 secretion is important for cancer stem cell (CSC) maintenance and is sufficient to induce CD44+:CD24low/− phenotype in breast cancer cells." (PMID 27933272, 2016). "Murine breast cancer cell-derived osteopontin activated primary normal mammary fibroblasts and increased pro-inflammatory factors, such as CXCL1, CXCL2, IL-6 and COX-2." (PMID 26828520, 2016). "Some cytokines and growth factors (IL-1, IL-6, IL-11, TGF-β, and VEGF) stimulate the proliferation and invasion of breast cancer cells, whereas others (IL-12, IL-18, and IFN) suppress breast cancer progression." (PMID 27484639, 2016). "This is in agreement with a previous report that MSC-secreted IL-6 facilitates cancer cell migration by persistent activation of MAPK, AKT and p38MAPK in breast cancer cells." (PMID 27531897, 2016). "After showing PAC-dependent inhibition of IL-6/MCP-1 expression and secretion from breast cancer cells we sought to test the effect of PAC on the paracrine effects of these cells on breast stromal fibroblasts." (PMID 27465411, 2016). "Fascin expression is induced by a variety of cytokines such as interleukin-6 (IL-6) and oncostatin M via transactivation of signal transducers and activators of transcription 3 (STAT3) in breast cancer cells." (PMID 27036017, 2016). "High levels of the inflammatory cytokine IL‐6 are correlated with poor prognosis in breast cancer 17, and IL‐6 trans‐signaling has been suggested to affect directly EMT6 and 4T1 breast cancer cell aggressiveness, leading to increased metastasis." (PMID 26725371, 2016). "After activated by IL-6 derived from metastasizing breast cancer cells, MDSCs can express both IL-6 and soluble IL-6Rα, which stimulate STAT3 phosphorylation through IL-6 trans-signaling in breast cancer cells." (PMID 27542274, 2016). "Induction of IL-6 production by the adipokine leptin in breast cancer amplifies STAT3 signaling, and phosphorylation of STAT3 is significantly reduced by IL-6 neutralizing antibodies." (PMID 26840088, 2016). "The effect on IL-6 and MCP-1 is of great importance since these two cytokines play important roles in the spread of various types of cancer, including breast carcinomas." (PMID 27465411, 2016). "In summary, an interaction between CD40 on MDA-MB231 breast cancer cells and CD40L on activated T cells increases the production of Th17 differentiating cytokines including TGF-β, IL-1β, IL-6, and IL-21." (PMID 25992978, 2015). "On the other hand, the secretion of IL-6, IL-1β and TNF was significantly lower in breast cancer patients." (PMID 25992611, 2015). "Among them, IL-6, IL-8 and CXCL1, previously shown to be important for breast cancer CSCs10, 11, 26, were the top three cytokines that seemed to be most abundantly detected and downregulated following IRAK1 knockdown." (PMID 26503059, 2015). "Leptin, IL-6, TNF-α, IFG, and other hormones are upregulated in obese women and contribute to a state of “chronic inflammation”, which can promote breast cancer growth." (PMID 26000019, 2015).
breast cancer (continued). "In conclusion, we have shown that IL-6 paracrine signaling between DCIS cells and CAFs is a key mediator of early stage breast cancer cell proliferation and migration." (PMID 26268945, 2015). "Our findings describe a novel signaling network in which YB-1 regulates IL-6, and vice versa, creating a positive feed-forward loop driving EMT-like metastatic features during breast cancer progression." (PMID 26512918, 2015). "We compared expression of the ligand IL6 and its target receptor GP130 in each of the breast cancer subtypes." (PMID 26173622, 2015). "From the study, we found that IL6 and CCL5 are overexpressed in basal breast cancer, suggesting their potential as therapeutic targets." (PMID 26173622, 2015). "TRF has showed the anti-cancer biologic function and also found to decrease the levels of IL-6, IL-8 and VEGF related to angiogenic in HUVEC and 4T1 mouse mammary cancer cells." (PMID 25807493, 2015). "IL6 and CCL5 gene expression are basal breast cancer specific, whereas high gene expression of GP130 was observed in luminal A/B." (PMID 26173622, 2015). "Activation of the PI3K/AKT pathway, IL-6/JAK2/STAT3 pathway, and stem cell-like characteristics contribute to the poor outcomes of metastatic breast cancers." (PMID 26515594, 2015). "Previously, we identified that key molecules (IL6, CSF2, CCL5, VEGFA, and VEGFC) secreted by tumor cells and stromal cells in basal breast cancer can promote metastasis." (PMID 26173622, 2015). "Of note, the pSTAT3-GS was positively correlated with IL6 (r = 0.4, P = 4.72e−05), which is the principal cytokine pathway through which STAT3 is activated in breast cancer and a surrogate of stromal reactivation." (PMID 26234940, 2015). "Autophagy, a critical process for breast cancer stem cells (CSC), maintains the cell stemness of breast CSC by regulating the secretion of IL-6." (PMID 26528857, 2015). "The proinflammatory cytokines and chemokines secreted by macrophages and adipose cells, including TNF-α, IL-6, MCP-1 and leptin, can directly stimulate breast cancer cell proliferation and invasion." (PMID 26132316, 2015). "SRF, YAP, TAZ (WWTR1) and IL6 are consistently upregulated in BLBC, normal-like breast cancer and claudin-low subtypes." (PMID 26671411, 2015). "Following the generation of trastuzumab resistance in HER2+ breast cancer cells with PTEN deletion, the mRNA and protein level of inflammatory cytokines IL-6 and IL-8 were dramatically unregulated." (PMID 26522776, 2015). "Together, these findings provide evidence that sulforaphane (SF) is able to disrupt the IL-6/NF-κB positive feedback loop that PTEN inactivated, trastuzumab resistant, breast cancers are reliant on." (PMID 26522776, 2015). "In the present study, we found that LPS upregulated BLT2 in aggressive breast cancer cells and that depletion of BLT2 attenuated the ability of LPS to stimulate invasiveness and biosynthesis of IL-6 and IL-8 in these cells." (PMID 25691060, 2015). "To extend our findings to human breast cancer, we examined expression levels of SRF, YAP/TAZ and IL6 in human breast cancer patients by analysing microarray data from various breast cancer study cohorts." (PMID 26671411, 2015). "STAT3 was activated by IL-6 in myeloma and prostate cancer cells, hepatocyte growth factor (HGF) and its receptor (c-MET) in leiomyosarcoma and breast cancer cells, and Src in breast cancer and melanoma cells." (PMID 24675568, 2014). "Our transcriptomic analysis confirmed previous findings showing that LPA induces the expression of the pro-osteoclastic cytokines IL6 and IL8 through LPA1 in breast cancer cells." (PMID 24828490, 2014). "Down-regulation of Interleukin-6 and its receptor (F11) results in growth inhibition of MCF-7 breast cancer cells, while high affinity of Insulin receptor binding (F7) has been observed in the same cells." (PMID 24997799, 2014).
breast cancer (continued). "Both RET and FAK inhibition impaired IL-6-induced migration and metastatic ability of breast cancer cells, and, conversely, when FAK is inhibited, RET-induced and IL-6-induced migration is abolished." (PMID 24467886, 2014). "Recently, some research groups have reported that IL-6 contributes to tumor metastasis and EMT in breast cancer and ovarian cancer via the JAK/STAT3 signaling pathway." (PMID 24789104, 2014). "IL-6, whose expression was up-regulated in the latter tumors, is a well known inducer of EMT and mediates trastuzumab resistance in breast cancer." (PMID 25362644, 2014). "They used mistletoe lectin I along with adriamycin and interleukin 6 (IL6) as reference compounds and carried out their studies using various human breast cancer cell lines." (PMID 25136622, 2014). "Circulating levels of the inflammatory cytokines IL-6 and TNF-α have also been used as evidence of aberrant HPA axis regulation in breast cancer patients and other populations." (PMID 24731917, 2014). "Ascorbate supplemented gulo KO mice had profoundly reduced levels of IL-6 compared to ascorbate-deprived gulo KO mice in both the melanoma B16FO and breast cancer 4T1 studies." (PMID 23175106, 2013). "To elucidate the relationship between MDSC recruitment and distant metastasis of cancer cells, we created a murine breast cancer model using 4T1 and EMT6 breast cancer cells, which exhibit differential IL-6 expression." (PMID 24021059, 2013). "Interleukin-6 (IL-6) and vascular endothelial growth factor (VEGF) secreted from MSCs increases the migration of breast cancer cell lines." (PMID 25177494, 2013). "Our results indicate that plasma, IL-6, and TNF-α promote breast cancer cell growth as aggregates and induce adhesive recruitment of BCa cells on E-selectin coated surfaces under flow." (PMID 23372803, 2013). "Cytokines produced by cancer tissue and the expression of interleukin (IL)-1β, IL-6, IL-8, IL-10, IL-12, and IL-19, monocyte-chemoattractant-protein (MCP-) 1, and macrophage-inflammatory-protein- (MIP-) 1β are upregulated in breast cancer." (PMID 23710200, 2013). "Chemotherapeutic agents increased the levels of IL-2, IL-6, interferon-gamma (INF-γ) and decreased the production of IL-1 and tumour necrosis factor-alpha (TNF-α) in women with advanced breast cancer who responded to treatment." (PMID 23320561, 2013). "The combination of interleukin-6 (IL-6) and vascular endothelial growth factor A (VEGF) secreted from mesenchymal stem cells increases the ability of breast cancer cell lines to migrate." (PMID 24147217, 2013). "As IL6 had been shown to be a pleiotropic cytokine with both tumor-promoting and inhibitory activity, the up-regulation of the expression of IL6 mRNA in the SN-F11/12-treated MDA-MB-231 cells may cause an inhibitory effect to the growth of the breast cancer cell line." (PMID 23874655, 2013). "This recruitment enhances tumor growth through the secretion of an abundance of growth factors from ASCs, such as IL-6, CCL5 and PDGR, which have been shown to contribute to both the breast cancer tumorigenesis and the metastasis of breast cancer cells." (PMID 24176089, 2013). "Changes in the relative concentration of some cytokines, such as IL-1, IL-6, IL-11, and IL-19, and transforming-growth-factor- (TGF-) β, mediated both directly and indirectly by the tumor stimulate breast cancer proliferation and invasion." (PMID 23710200, 2013). "On the contrary, in the ER(-) breast cancer cell lines HS578T and MDA-MB-231, IL-6 is related to a drug-resistant phenotype with increased expression of MDR-1." (PMID 23552194, 2013). "We now show that the breast cancer cells T47D, are capable of producing CD44+ cells with stem-like properties on exposure to IL-6, which suggests that IL-6 promotes the induction of CSCs." (PMID 22134360, 2012).
breast cancer (continued). "Herein, we provide evidence that the inflammatory cytokine, IL-6, is capable of generating CD44+ cells with stem-like properties through inducing EMT in the T47D breast cancer cells." (PMID 22134360, 2012). "Among the factors secreted by macrophages, IL-6 and TNF-α have important implications for breast cancer." (PMID 22529912, 2012). "We had previously reported that IL-6, KC, MCP-1, VEGF, and MIP-2 were secreted by osteoblasts and increased in the presence of breast cancer cells in vitro and in vivo." (PMID 22315691, 2012). "Coculture of adipocytes with breast cancer cells resulted in adipocyte activation and secretion of MMP11, as well as proinflammatory cytokines IL-6 and IL-1β." (PMID 22482060, 2012). "Next, we measured IL-6 production from breast cancer cell culture supernatants and found that cells expressing a high level of TG2 produced a large amount of IL-6." (PMID 21967801, 2011). "Primary tumor growth in the mammary fatpads and distant hematogenous metastasis of breast cancer cells into the lung was also dependent on TG2 and downstream IL-6 expression levels." (PMID 21967801, 2011). "Complete inhibition of primary tumor growth and distant lung metastasis by IL-6-knockdown compared with some residual tumor growth and metastases by TG2-knockdown in the breast cancer cells." (PMID 21967801, 2011). "This study investigated the effects of Ulinastatin (UTI) and docataxel (Taxotere, TAX) on tumor growth and expression of interleukin-6 (IL-6), interleukin-8 (IL-8), and tumor necrosis factor-α (TNF-α) in breast cancer." (PMID 21345194, 2011). "In breast cancer patients, depressed serum levels of IL-2, GM-CSF, IFN-γ and enhanced TNF-α and IL-6 amounts were reported in comparison with controls and some of these immune dysfunctions are also present in early-stage tumors." (PMID 22112244, 2011). "Serum levels of IL-6 correlates well with the extent of tumor invasion, LN metastasis, distant metastasis and TNM staging thus enveloping all aspects of breast cancer." (PMID 21294915, 2011). "The principal objective of this study was to determine the relationship between serum IL-6 and CRP levels and staging and prognosis in breast cancer patients." (PMID 21294915, 2011). "The primary objective of this study was to determine the preoperative serum levels of IL-6 and CRP in breast carcinoma, and to correlate them with the staging of the disease and the prognosis." (PMID 21294915, 2011). "It has been shown that elevated serum levels of IL-6 and MMP-2 in breast cancer patients correlates with the stage and the severity of the disease." (PMID 20723242, 2010). "In breast cancer (DCIS), both oncostatin M (OSM) and interleukin-6 (IL-6) have been proposed to regulate the expression and activity of S100A7 by regulating PI3K, STAT3 and Erk signaling." (PMID 20689826, 2010). "In our study, serum analysis of cytokine proteins revealed higher expression of M-CSF, IL-17, IL-6, TNF-α, and VegF in the arthritic mice only when challenged with 4T1 metastatic breast cancer cells." (PMID 19643025, 2009). "STAT3 increases production of IL-6, which can further stimulate and prolong STAT3 activation in breast cancer epithelial cells in an autocrine as well as a paracrine fashion, as shown here in this manuscript." (PMID 18939993, 2008). "Our results further demonstrated that MCF-10A cells treated with conditioned media from MDA-MB-231 breast cancer cells can allow MCF-10A cells to produce and secrete their own IL-6." (PMID 18939993, 2008). "Although IL-6 expression in early-stage breast carcinomas has been correlated with low grade, oestrogen receptor status and good prognosis, several studies have shown that IL-6 may contribute to disease progression, particularly in advanced breast cancer patients." (PMID 12771987, 2003).
breast cancer (continued). "We therefore investigated the effects of LRP5-overexpressing osteocyte-derived CM on the expression of proteins associated with tumor progression (e.g., MMP9, Snail, cleaved caspase-3, IL-6, TGF-β1) and on breast cancer cell proliferation, migration, and invasion of tumor cells." (PMID 41596426, 2026). "Importantly, IL-6 and CXCL-8 promoted the migration of MCF10A cells and HER2-positive breast cancer cells." (PMID 41495793, 2026). "The regulatory mechanisms of CAA in breast cancer are complex, including inflammatory adipokine secretions such as IL-1β, CCL2, TNFα, CCL5, and leptin, as well as IL-6 metabolic reprogramming by altering the metabolism of macronutrients and remodeling of the extracellular matrix." (PMID 39858015, 2025). "In addition, TAMs secrete high levels of IL-6 increasing stemness markers (i.e. SOX2, OCT3/4 and NANOG) and consequently CSCs expansion in breast cancer cells via STAT3 pathway supporting tumor cells migration and angiogenesis." (PMID 39981232, 2025). "A recent study revealed that activation or increases in multiple pathways, such as the TGF-β signaling pathway, the inflammatory response, the IL6-JAK-STAT3 and TNF-γ–NF–kB signaling, and the IFN-γ response, have been connected to the onset or progression of breast cancer." (PMID 40584290, 2025). "In breast cancer, CSCs can emerge after treatment of HER2-amplified tumors, a process mediated by IL-6 signaling that operates in an autocrine fashion to induce a CSC phenotype in response to HER2 inhibition, similar to the effect of notch signaling in survival and proliferation of CSCs." (PMID 40430044, 2025). "In patients with breast cancer that have the luminal B HER2-positive molecular subtype, an anti-cytokine therapy based on IL-6 and IL-8 receptor inhibitors may be useful." (PMID 40584290, 2025). "The pro-oncogenic transcription factor STAT3 forms a positive feedback loop with some of the inflammatory cytokines, including IL-6, and promotes MMP13 expression in murine breast cancer CAFs; furthermore, MMP13 plays an important role in maintaining the function of CAFs." (PMID 40243781, 2025). "Icariin enhances macrophage phagocytosis, reduces spleen and thymus indices, downregulates pro-inflammatory cytokines (IL-6, IL-8, IL-1β) in cervical cancer (SiHa) cells, and inhibits TGF-β1 protein expression in breast cancer (MDA-MB-231) cells, suggesting its immunomodulatory effects." (PMID 40490812, 2025). "Moreover, COPS6 was found to be not only a mediator of IL-6 secretion in the tumor microenvironment, but also a negative regulator of CD8+T cells tumor infiltration in breast cancer." (PMID 40040705, 2025). "Therefore, this study aims to address the following question: What is the prognostic relevance of serum IL-6 and TNF-alpha levels on overall survival and treatment response in women with breast cancer?" (PMID 40558287, 2025). "Within the breast cancer microenvironment, exosomes containing ANXA2 stimulate the activation of MAPK and NF-κB signaling pathways in macrophages, thereby mediating the secretion of the chemokines IL-6 and TNF-α to remodel the microenvironment to support breast cancer cell survival." (PMID 39972459, 2025). "Therefore, it is critical to investigate the acute effects of different exercise modes on the expression of anti-cancer myokines, such as IL-6, OSM, decorin, and SPARC, and their effects on breast cancer cell growth (i.e., MDA-MB-231)." (PMID 40608178, 2025). "Although IL‐6 is known to drive cancer progression and therapeutic resistance, its role in mediating resistance to eribulin in breast cancer has not been previously investigated." (PMID 41189442, 2025). "Elevated IL-6 secretion from senescent cells and subsequent activation of STAT3 reinforce a pro-inflammatory microenvironment that promotes tumorigenic potential in breast cancer." (PMID 41148817, 2025).